OR4F21 (olfactory receptor family 4 subfamily F member 21)
Description:
Odorant receptor.
Synonyms: OR4F21P
Tractability: Antibody: UniProt places it where antibodies can reach, with medium confidence; UniProt predicts a signal peptide or a membrane-spanning region; its Gene Ontology location is reachable by antibodies, with medium confidence.
Gene: Protein-coding gene on chromosome 8 (166,086 to 167,024, reverse strand). Ensembl gene ENSG00000176269.
Subcellular location: Cell membrane
Pathways (Reactome):
Sensory Perception: Expression and translocation of olfactory receptors
Gene Ontology:
Molecular function: olfactory receptor activity; G protein-coupled receptor activity
Biological process: detection of chemical stimulus involved in sensory perception of smell; G protein-coupled receptor signaling pathway
Cellular component: plasma membrane; membrane
Homologues: Orthologues: rat Or4f7 (82% identical), rat Or4f7c (82% identical), mouse Or4f7 (81% identical). Paralogues in human: OR4F16 (99% identical), OR4F29 (99% identical), OR4F3 (99% identical), OR4F15 (71% identical), OR4F6 (67% identical), OR4F4 (57% identical), OR4F5 (57% identical), OR4F17 (56% identical), OR4K5 (53% identical), OR4K17 (52% identical), OR4K1 (51% identical), OR4K15 (51% identical), and 116 more.